ELN (elastin)
Diseases named in the same sentence as ELN in open-access papers (continued):
Sharing a sentence is not in itself a finding about the gene and the disease.
endothelial dysfunction (58 papers, 2014 to 2026). In vascular diseases, endothelial dysfunction is a systemic pathological state of the endothelium (the inner lining of blood vessels) and can be broadly defined as an imbalance between vasodilating and vasoconstricting substances produced by (or acting on) the endothelium. "In postmenopausal women, estrogen deficiency alsoexacerbates endothelial dysfunction, promotes the rupture of arterial elastin,leads to collagen accumulation, and increases arterial stiffness." (PMID 40160598, 2025). "It is to some extent caused by changes in the arterial walls, where elastin is degraded and collagen is deposited, but also by endothelial dysfunction and inflammation." (PMID 39466791, 2024). "These include elastin fiber degradation, increased collagen quantity, cardiomyocyte loss and hypertrophy, and endothelial dysfunction with diminished capacity to produce NO and other vital peptides." (PMID 36983321, 2023). "In IR angiotensin II, oxidative stress, endothelial dysfunction, pro-inflammatory cytokines, and adhesion molecules activate matrix metalloproteinases (MMPs), which cause fragmentation of elastin molecules and increase collagen stiffness." (PMID 29375617, 2017). "Indeed, pathophysiological alterations in the arterial wall make older people more prone to conditions such as isolated systolic hypertension, as changes including endothelial dysfunction and elastin calcifications increase the risk." (PMID 31698758, 2019). "Furthermore, arterial stiffness could be caused by endothelial dysfunction, and inflammation results in overproduction of abnormal collagen and reduces normal elastin resulting in vascular stiffness." (PMID 36826566, 2023). "These factors lead to endothelial dysfunction and structural changes in the arterial wall, such as increased collagen deposition and reduced elastin content, thereby elevating PWV." (PMID 40722589, 2025). "The aging process can contribute to arterial stiffness through several mechanisms, including oxidative stress, endothelial dysfunction, elastin degradation, collagen accumulation, arterial calcification, and chronic inflammation." (PMID 40364032, 2025). "This condition is related to the loss of arterial elasticity caused by structural and functional changes, such as calcium and collagen accumulation, rupture of elastin fibers, and endothelial dysfunction." (PMID 41059807, 2025). "Aging causes progressive structural changes in vascular walls, including increased collagen deposition, reduced elastin content, endothelial dysfunction, and alterations in calcium homeostasis within vascular smooth muscle cells." (PMID 41393262, 2025). "Chronic persistent inflammation, oxidative stress, and endothelial dysfunction disrupt the balance between elastin and collagen (with elastin degradation and collagen accumulation), leading to increased arterial rigidity." (PMID 40423077, 2025). "Smoking contributes to endothelial dysfunction and promotes chronic vascular inflammation, which accelerates the degradation of extracellular matrix components such as elastin and collagen in the aortic wall." (PMID 40800016, 2025). "Histological analysis of the cerebrum predominantly revealed endothelial dysfunction, as supported by numerous studies demonstrating disturbances in the expression of collagen type IV, laminin, and elastin." (PMID 41228556, 2025). "Another well‐studied mouse model is the BubR1 mice, show endothelial dysfunction, decreased levels of elastin, fibrosis, thinning of both the arterial wall and the inner diameter, VSMC loss, and impaired angiogenesis." (PMID 38451018, 2024). "Biological pathways for development of COPD include inflammation and accelerated aging which results in elastin degradation, endothelial dysfunction, and imbalances of protease and antiproteases." (PMID 38388652, 2024).
endothelial dysfunction (continued). "Which involves chronic, low-grade inflammation, extracellular matrix (ECM) remodeling including elastin degradation, medial thickening, endothelial dysfunction, phenotypical switching of vascular smooth muscle cells (VSMCs), calcification, and fibrosis." (PMID 37895059, 2023). "Impaired collagen-elastin ratio, calcification of blood vessels, endothelial dysfunction, increased intima media-thickness, and genetic determinants can produce arterial wall remodeling." (PMID 37510208, 2023). "Exercise also improves endothelial dysfunction and increases elastin content, thereby restoring normal arterial function." (PMID 34442203, 2021). "PWV, an objective measure of endothelial dysfunction and arterial stiffness, becomes elevated secondary to changes in the vascular wall especially a higher collagen-elastin ratio that decreases dispensability." (PMID 34210226, 2021). "Chronic inflammation and oxidative stress lead to endothelial dysfunction, collagen and elastin degradation, changes in the composition and hydration state of proteoglycans, and medial calcification, which gradually cause arterial stiffness." (PMID 34746254, 2021). "Interconnection between inflammatory pathways and various large artery stiffening mechanisms (degradation of elastin, calcification of medial, endothelial dysfunction) is mediated by increasing inflammatory cells." (PMID 34330221, 2021). "The aged artery is characterized by endothelial dysfunction, chronic inflammation, migration and proliferation of vascular smooth muscle cells, elastin fragmentation, extracellular matrix deposition, and matrix calcification/amyloidosis/glycation." (PMID 32498283, 2020). "Arterial aging is accompanied by vascular remodeling with vascular elastin degeneration, collagen deposition in the arterial wall, endothelial dysfunction, and increases in arterial stiffness." (PMID 31450550, 2019). "Knockout of vimentin, but not of synemin, resulted in increased carotid stiffness and contractility and endothelial dysfunction, independently of blood pressure and the collagen/elastin ratio." (PMID 28912461, 2017). "There are many other factors such as elastin fragmentation, endothelial dysfunction and advanced glycation that affect aortic stiffness other than calcification." (PMID 24626513, 2014). "Endothelial dysfunction isaccompanied by the inability of aortic wall smooth muscle cells to generate forcethrough the elastin-contractile units in response to pulsatile blood flow.Current pharmacotherapy includes a wide range of medications, includingantihypertensive and antidiabetic." (PMID 39076501, 2024). "As already mentioned potential concurrent damage to elastin in the artery and the alveoli as well as potential endothelial dysfunction in the coronary and pulmonary vasculature may be one link explaining our results." (PMID 35263363, 2022). "However, there are other mechanisms mediating increased vascular stiffness, such as collagen and elastin disarray, calcium deposition, endothelial dysfunction, and the number of vascular smooth muscle cells (VSMCs)." (PMID 34950048, 2021). "Decreased NO and oxidative excess may induce matrix metalloproteinases (MMPs), usually MMP-2 and MMP-9, which break down the fibrous cap containing collagen, elastin, and proteoglycans, resulting in endothelial dysfunction." (PMID 25311097, 2014). "The shared effect of endothelial dysfunction, chronic low-grade inflammation, glycation product formation and changes in structure of elastin and collagen fibers in the arterial wall are all pathophysiological mechanisms suggested to contribute to the increased arterial stiffness in diabetes." (PMID 25405619, 2014). "The strong association between smoking and AA aligns with known pathophysiological mechanisms, might including elastin degradation and extracellular matrix remodeling, vascular inflammation and oxidative stress, smooth muscle cell apoptosis, hemodynamic stress, and endothelial dysfunction." (PMID 40800016, 2025).
endothelial dysfunction (continued). "Thus, pathological values of DLCO and IOS in patients with CAD, may indicate potential mechanisms such as concurrent damage to elastin in the artery and the alveoli as well as potential endothelial dysfunction in the coronary and pulmonary vasculature." (PMID 35263363, 2022). "The underlying process includes a complex interplay between factors, among which are collagen-elastin and metalloprotease (MMP) balance as well as endothelial dysfunction." (PMID 36556173, 2022). "Finally, we did not explore the degradation of elastin and collagen in the vessel walls which is an important part of endothelial dysfunction." (PMID 36012201, 2022). "The mechanisms underlying the relationship between Hcy and arterial stiffness are not entirely clear but may include endothelial dysfunction, smooth muscle cell proliferation, collagen synthesis, and deterioration of elastin, resulting in impaired arterial compliance." (PMID 24475061, 2014).
supravalvular aortic stenosis (51 papers, 2010 to 2025). SupraValvar Aortic Stenosis (SVAS) is characterized by the narrowing of the aorta lumen (close to its origin) or other arteries (branch pulmonary arteries, coronary arteries). "Elastin is an important component of the arterial wall, and one of the disorders caused by a heterozygous mutation in the ELN gene is supravalvular aortic stenosis, which manifests with arteriopathy, with multiple pulmonary and systemic arterial stenoses." (PMID 40650005, 2025). "Mutations in the ELN gene can result in improper tropoelastin production or assembly, leading to diseases like supravalvular aortic stenosis (SVAS) and Williams-Beuren syndrome (WBS), where elastic fiber deficiency contributes to arterial stenosis 152,153." (PMID 41281748, 2025). "There is also the possibility that in individuals with such mutations, the phenotypes can range from severe to mild and even asymptomatic, as was described by Li D in cases involving ELN mutations and supravalvular aortic stenosis." (PMID 40650005, 2025). "More recently, a proband and his father were identified with a variant in the start codon of ELN (c.2T > C; p.M1T), causing elastin haploinsufficiency and supravalvular aortic stenosis (SVAS, MIM #185500)." (PMID 35741248, 2022). "HiPS-derived smooth muscle cells (hiPS-SMCs) have been used to characterize molecular level mechanisms behind elastin deficiency causing supravalvular aortic stenosis and pulmonary stenosis." (PMID 34208537, 2021). "In non-syndromic supravalvular aortic stenosis with a nonsense mutation, mRNA degradation of mutant alleles leads to a large numbers of premature termination codon mutations in ELN, resulting in insufficient ELN levels." (PMID 34238994, 2021). "Cardiovascular abnormalities like supra valvular aortic stenosis seen in WS are considered to be caused by the deletion of elastin." (PMID 32303053, 2020). "Most reported mutations within the ELN gene cause supravalvular aortic stenosis and autosomal dominant cutis laxa." (PMID 33086603, 2020). "ELN haploinsufficiency causes vascular abnormalities, such as supra-valvular aortic stenosis (SVAS), which correspond to a thickening of the vessel wall." (PMID 31138170, 2019). "An eighteen-month-old infant with moderate hypercalcemia and distinctive facial features together with supravalvular aortic stenosis was noted to have an elastin gene mutation on chromosome 7q.11.23 in fluorescent in situ hybridization analysis." (PMID 28443817, 2017). "Both elastin knockout mice and humans with supravalvular aortic stenosis characterized by loss-of-function mutations on one elastin allele have uncontrolled SMC proliferation in the intima leading to arterial stenosis and death." (PMID 26637293, 2015). "The cardio-vascular defects in this syndrome were found to be due to loss of elastin, and mutations in elastin were identified in individuals with isolated supravalvar aortic stenosis." (PMID 21532774, 2010). "Thus, the explanation of the phenotypic feature supravalvular aortic stenosis in WS is thought to be haploinsufficiency of the elastin gene, because individuals with loss-of-function mutations in this gene have the identical phenotypic abnormality." (PMID 25315429, 2014). "Supravalvular aortic stenosis (SVAS), common in WS, is mainly caused by mutations in the elastin (ELN)gene." (PMID 39733135, 2024). "In humans, supravalvular aortic stenosis (SVAS) has been linked to mutations in the elastin gene (ELN)." (PMID 35229725, 2022). "Decreased elastin in humans is associated with development of an autosomal dominant disease, supravalvular aortic stenosis (SVAS)." (PMID 31857579, 2019). "This disease pattern is characteristic for supravalvular aortic stenosis (SVAS) which is caused by mutations in the elastin gene." (PMID 29243171, 2018).
supravalvular aortic stenosis (continued). "Thus, hemizygosity for the ELN gene is thought to cause the supravalvular aortic stenosis, LIMK1 hemizygosity is implicated in the impaired visuospatial constructive cognition and GTF2I hemizygosity is thought to contribute to the mental retardation in WS patients." (PMID 25315429, 2014). "Elastin plays a critical role in the development of the cardiovascular, skin and respiratory system, as demonstrated when deletions and mutations in the elastic fibers result in supravalvular aortic stenosis (SVAS), William-Beuren syndrome (WBS) or cutis laxa (CL)." (PMID 22818364, 2012). "Monoallelic variants of the ELN gene are known to be responsible for autosomal dominant cutis laxa (OMIM #123700) and supravalvular aortic stenosis (OMIM #185500)." (PMID 40259928, 2025). "Mutations within the ELN gene are associated with various elastinopathies, including autosomal dominant cutis laxa (ADCL, OMIM 123,700) and supravalvular aortic stenosis (SVAS, OMIM 18,500)." (PMID 37980465, 2023). "In humans, mutations affecting the elastin gene have been associated with diseases such as Williams–Beuren syndrome (WBS), autosomal dominant cutis laxa (ADCL), and non-syndromic supravalvular aortic stenosis (SVAS)." (PMID 37408270, 2023). "The pathognomonic lesion for diseases of elastin insufficiency is a focal stenosis of the ascending aorta, also known as supravalvar aortic stenosis (SVAS), but long segment stenosis also occurs commonly." (PMID 35665242, 2022). "The alteration of elastic fibers leads to cardiovascular dysfunctions, as observed in elastin haploinsufficiency in mice (Eln+/-) or humans (supravalvular aortic stenosis or Williams–Beuren syndrome)." (PMID 36362244, 2022). "Additionally, the generation of hiPSC-derived SMCs allowed to recapitulate the multiple features of supravalvular aortic stenosis (SVAS) including mutations in the elastin (ELN) gene." (PMID 34262897, 2021). "A reduction in ELN expression was also observed in cutaneous fibroblasts and aortic smooth muscle cells in affected non-syndromic supravalvular aortic stenosis patients, thus, supporting the role of ELN haploidy as a pathogenesis of vascular lesions." (PMID 34238994, 2021). "Due to mutations in the ELN gene for elastin, about 77% of patients with WBS have supravalvular aortic stenosis, probably owing to the fact that NCCs participate in the development of ascending aorta and arch of the aorta." (PMID 33375093, 2020). "Identical vascular features, most prominently supravalvular aortic stenosis, are also found in patients with heterozygous deletions or disruptions of the ELN gene, implicating elastin haploinsufficiency in this phenotype." (PMID 22319452, 2012). "Pathogenic variants in ELN cause supravalvar aortic stenosis but are not known to cause AVS/BAV, thus it is uncertain if it is a phenotype modifier in the family with a CASZ1 variant." (PMID 35737725, 2022). "Likewise, clinical studies involving cohorts of patients with genetic elastin deficits (patients with supravalvular aortic stenosis or Willliams–Beuren syndrome) presented not only with vascular stiffening but also with AHT35,36." (PMID 34782679, 2021). "Elastin-driven genetic diseases are a group of complex diseases driven by elastin protein insufficiency and dominant-negative production of aberrant protein, including supravalvular aortic stenosis (SVAS) and autosomal dominant cutis laxa." (PMID 37980465, 2023). "The inherent ability of elastin to self-aggregate was described as a coacervation phenomenon and coacervation might play a critical role in the elastogenesis process which once impaired may induce elastin haploinsufficiency disorders including supravalvular aortic stenosis." (PMID 34917605, 2021).
supravalvular aortic stenosis (continued). "One study that examined two families with a partial WS phenotype, including supravalvular aortic stenosis (SVAS) and deficits in visuospatial construction, found that affected family members were hemizygous for the elastin (ELN) and LIM-Kinase1 (LIMK1) genes, which lie within the WSCR." (PMID 25057328, 2014).